TEN1-CDK3 (TEN1-CDK3 readthrough (NMD candidate))
Synonyms: C17orf106-CDK3
Gene: Protein-coding gene on chromosome 17 (75,979,231 to 76,005,999, forward strand). Ensembl gene ENSG00000261408.
Genetic constraint (gnomAD): Missense variants: 149 observed, 165.08 expected, observed/expected ratio (o/e) 0.9, 90% interval 0.79 to 1.03. Synonymous variants: 65 observed, 68.35 expected, observed/expected ratio (o/e) 0.95, 90% interval 0.78 to 1.17.